WNT5A (Wnt family member 5A)
Diseases named in the same sentence as WNT5A in open-access papers (continued):
Sharing a sentence is not in itself a finding about the gene and the disease.
pancreatic cancer (continued). "Thus, our study shows that the Lin28b-Wnt5a axis plays a critical role in bidirectional crosstalk between pancreatic tumor epithelium and TME and results in a pro-‍tumorigenic contexture." (PMID 37898598, 2023). "Heatmap analysis in colorectal, stomach, and pancreas cancer patient datasets showed a consistent overlap between LBH overexpression and WNT signaling genes associated with pathway activation, i.e., WNT2, WNT5A, WNT11, LEF1, TCF4 or TCF7, CCTNB1, CCND1, JUN, DKK3." (PMID 37268816, 2023). "Moreover, compound 2 was found to induce apoptosis mediated by the activation of Wnt5a/Cyclin D1 signaling pathway in human pancreatic tumor cells." (PMID 36225350, 2022). "Since gemcitabine is a cell cycle specific drug, these studies have found that WNT5A mediated gemcitabine chemoresistance was via the regulation of cell cycle, which suggests WNT5A as an effective gemcitabine chemoresistance predictor and a target for chemotherapeutic response in pancreatic cancer." (PMID 29882812, 2018). "However, WNT5A is thought to induce chemoresistance in pancreatic cancer through enhanced PI3K/Akt signaling that affects the G1/S phase transition." (PMID 29882812, 2018). "Moreover, overexpression of the Wnt5a protein in the pancreatic cancer cell lines PANC-1 and BXPC-3 induced tumor cell proliferation and decreased apoptosis in an orthotopic nude mouse model." (PMID 27571105, 2016). "TGF-β also induces WNT-5A expression in pancreatic cancer cells." (PMID 24728340, 2014). "Next, we examined the biological functions of Wnt5a in pancreatic cancer." (PMID 24156409, 2013). "We next checked the effect of Wnt5a on the EMT of pancreatic cancer cells." (PMID 24156409, 2013). "Overall, 81.3% (109/134) of all pancreatic cancers showed positive expression of Wnt5a." (PMID 24156409, 2013). "Notably, siRNA-mediated silencing of β-catenin blocked recombinant Wnt5a-induced acquisition of the mesenchymal phenotype in pancreatic cancer cells." (PMID 24156409, 2013). "In this context, WNT5a promotes pancreatic cancer migration, proliferation and invasiveness." (PMID 24212973, 2011). "Similarly, CUTL1-upregulated Wnt5a significantly enhanced migration, proliferation and invasiveness in pancreas cancer cellls." (PMID 19849855, 2009). "Also, WNT-5A activates β-catenin signaling in pancreatic cancer cells and dermal fibroblasts." (PMID 26514730, 2016). "Interestingly, coculture experiments with pancreatic cancer cell line and fibroblast suggest that pancreatic cancer cells may induce fibroblast Wnt5a secretion by soluble factors." (PMID 24212973, 2011). "Specifically, the coculture of pancreatic cancer cells and adipocytes induces the JAK/STAT3 pathway, leading to increased Wnt5a expression and adipocyte reprogramming." (PMID 36670988, 2023). "Riluzole inhibited the expression of β-catenin, Wnt3a, Wnt5a, WSP, TCF and LEF in both MIA PaCa-2 and AsPC-1 pancreatic cancer cells." (PMID 35773307, 2022). "Increased expression of long noncoding RNA LINC01133 is observed in pancreatic cancer, where it decreases the expression of DKK1 and increases the expression of Wnt5a, MMP-7, and β-catenin by binding to their promoters." (PMID 31480221, 2019). "A previous study indicated that up-regulation of Wnt5a promotes EMT and metastasis of pancreatic cancer cells." (PMID 29054966, 2017). "The effects of Wnt5a overexpression or silencing on the invasiveness and epithelial-to-mesenchymal transition (EMT) of pancreatic cancer cells were studied." (PMID 24156409, 2013). "Targeted reduction of β-catenin antagonized exogenous Wnt5a-induced EMT and invasiveness in pancreatic cancer cells." (PMID 24156409, 2013). "Upregulation of Wnt5a promotes EMT and metastasis in pancreatic cancer models, which involves activation of β-catenin-dependent canonical Wnt signaling." (PMID 24156409, 2013).
pancreatic cancer (continued). "Wnt5a is elevated in pancreatic cancer tissue versus surrounding non-cancerous tissues and promotes invasion and proliferation whilst inhibiting apoptosis." (PMID 35358569, 2022). "Cell-free DNA hypermethylation of BMP3, MESTv2, SST, TFPI2, TAC1, ALX4, HIC1, SFRP2, SEPT9v2 and WNT5A has not previously been described in the literature in relation to pancreatic cancer." (PMID 27891190, 2016). "Although the in vitro evidence indicated a master role of Wnt5a in inducing aggressive tumor phenotypes, the prognostic impact of Wnt5a expression in pancreatic cancer appears not to be of significance." (PMID 24156409, 2013). "Treatment with recombinant Wnt5a elevated the nuclear β-catenin level in pancreatic cancer cells, without altering the Ror2 expression." (PMID 24156409, 2013). "WNT5a is a classic β-catenin independent (non-canonical) Wnt that is commonly deranged in pancreatic cancer." (PMID 24212973, 2011). "In our system, due to the crosstalk between adipocytes and pancreatic cancer cells, we observed an increase in STAT3 phosphorylation in Tyr-705 in cancer cells; as a consequence of IL6/STAT3 signaling pathway activation we observed in MiaPaCa2 cells an increase in WNT5a expression." (PMID 26958939, 2016). "Moreover, in pancreatic cancer cells, an activation of the JAK-STAT3 pathway that could drive WNT5a activation, has been shown to be induced by inflammatory cytokines produced also by AT." (PMID 26958939, 2016). "Immunohistological analysis demonstrated that Wnt5a-overexpressing tumors exhibited increased expression of vimentin and decreased expression of E-cadherin, indicative of the occurrence of EMT, compared to control tumors derived from empty vector-transfected pancreatic cancer cells." (PMID 24156409, 2013).
Obesity (40 papers, 2012 to 2026). Accumulation of substantial excess body fat. "Another example is Wnt5a, a proinflammatory marker associated with obesity, which has been reported to be increased in granulosa cells of PCOS patients." (PMID 39063189, 2024). "On the other hand, in human subjects obesity has been reported to be associated with Wnt5a mRNA production primarily in visceral adipose tissues." (PMID 35478181, 2022). "In this study, we sought to identify the cellular source of Wnt5a secretion into the sera of obese mice and the mechanism underlying obesity-associated increases in Wnt5a expression." (PMID 35478181, 2022). "In this sense, given that the adipose tissue-liver axis seems to be relevant in the progression of NAFLD, in this study, we evaluated the SFRP5/WNT5A-PPARγ pathway in adipose tissue samples of women with different degrees of NAFLD associated to obesity." (PMID 36077270, 2022). "Subsequently, many studies have tried to elucidate the mechanisms through which Sfrp5 and Wnt5a are associated with obesity and cardiometabolic risk factors, as well as their potential role in developing new pharmaceutical compounds." (PMID 34371968, 2021). "Wnt5a is expressed in adipocytes and is upregulated in mice on a high fat diet and contributes to obesity-associated inflammation." (PMID 30524198, 2018). "Overall, these data suggest that increased WNT5A expression in visceral fat depots contributes to the low-grade systemic inflammation typically associated with obesity and visceral adiposity." (PMID 29229927, 2017). "IL-6 treatment restored insulin resistance in obese Wnt5a-deficient mice, suggesting this inflammatory cytokines in adipose tissue promote obesity-induced metabolic dysfunction." (PMID 27608847, 2016). "SFRP5 is a Wnt5a antagonist, therefore, SFRP5 expression loss exaggerated the pro-inflammatory effects of Wnt5a, which was shown to be induced by obesity." (PMID 27608847, 2016). "Genetic variants in Wnt5a have been associated with obesity in mice models." (PMID 28272483, 2017). "However, the associations between WNT5A variations and obesity related traits in human subjects are still unclear." (PMID 28272483, 2017). "Obesity is associated with elevated serum levels of pro-inflammatory wnt5a in humans." (PMID 22384249, 2012). "Inflammation associated with obesity is by far of a lower grade compared to the condition of sepsis, however, especially in severe obese individuals the amount of adipose tissue as a potential source of wnt5a is extremely increased." (PMID 22384249, 2012). "However, Wnt5a expression and its pro-inflammatory activity have also been linked to the pathogenesis of multiple chronic inflammatory diseases, including rheumatoid arthritis, psoriasis, colitis, atherosclerosis, and obesity." (PMID 28082976, 2016). "When the obesity group (n = 60) was classified according to the obesity class, the metaflammation markers under the study, leptin (p < 0.001), TNF-α (p = 0.007), and Wnt5a (p = 0.001), showed a significant increase with the higher obesity class." (PMID 39837875, 2025). "In obesity, Wnt5a promote adipogenesis and fat deposition in adipose cells via noncanonical Wnt signalling and inhibiting the canonical Wnt pathway." (PMID 39837875, 2025). "Serum leptin and Wnt5a showed significant differences between obesity classes I vs. III (p-values < 0.001 and = 0.002, respectively) and II vs. III (p-values < 0.001 and 0.006, respectively)." (PMID 39837875, 2025). "It was reported that Wnt5a ablation in mice with obesity reduces inflammation in adipose tissue and improves insulin resistance." (PMID 39837875, 2025). "Type 2 diabetes, dyslipidemia, obesity, and atherosclerosis are all inflammation-related diseases, with the WNT5A protein as a critical signaling molecule in the pathogenesis of various inflammatory disorders." (PMID 37542207, 2023).
Obesity (continued). "Wnt5a and CTGF, a YAP target gene can cooperate with TGF-β to induce sustained fibrosis, which is a hallmark of human obese WAT and causes obesity-induced chronic inflammation." (PMID 35478181, 2022). "To study the mechanism whereby obesity increases Wnt5a expression in adipocytes, we generated mature adipocytes by differentiating 3T3-L1 preadipocytes with adipogenic hormone." (PMID 35478181, 2022). "In the present study, skeletal muscle IGF‐1, Wnt3a, Wnt5a and Wnt7a mRNAs were all reduced in subjects with obesity." (PMID 35293040, 2022). "Several human studies that included age- and sex-matched controls did not detect a significant difference between males and females in terms of obesity-induced Wnt5a expression." (PMID 35478181, 2022). "This study showed that obesity increases Wnt5a production in subcutaneous WAT more so than in epididymal WAT in mice, whereas in man production in omental visceral fat is greater than from in subcutaneous WAT." (PMID 35478181, 2022). "Next, we wanted to evaluate the mRNA abundance of SFRP5, WNT5A and PPARγ and their link with obesity, so we classified the cohort into NW subjects (control group) and MO patients." (PMID 36077270, 2022). "In line with previous reported that obesity increases Wnt5a protein levels in the sera of humans and mice, we found that serum Wnt5a protein levels were higher for HFD fed mice than ND fed mice." (PMID 35478181, 2022). "Wnt5a is present in serum and its serum levels are correlated with the presence of chronic diseases, such as atherosclerosis, obesity, and rheumatoid arthritis, which suggests Wnt5a has endocrine functions." (PMID 35478181, 2022). "The Sfrp5/Wnt5a regulatory system is still relatively unexplored, however, current evidence indicates that it plays a pivotal role in obesity, even in childhood and adolescence." (PMID 34371968, 2021). "This review summarizes the current knowledge on the novel regulatory system of anti-inflammatory Sfrp5 and pro-inflammatory Wnt5a, and their relation to obesity and obesity-related complications." (PMID 34371968, 2021). "Wnt5a, another initiator that activates the canonical and non‐canonical Wnt pathways, is closely related to a variety of metabolic disorders such as obesity and T2DM." (PMID 34042263, 2021). "Recent evidence suggests that Sfpr5 and Wnt5a play a key role in the pathogenesis of obesity and its metabolic complications." (PMID 34371968, 2021). "Clinical studies have been conducted to delineate the role of Sfrp5 and Wnt5a in obesity, and the regulation of their secretion in an obesogenic environment." (PMID 34371968, 2021). "Wnt5a signaling has recently been proposed to play an essential role in obesity- or diabetes-induced metabolic dysfunction and inflammation." (PMID 33462195, 2021). "The purpose of this review is to summarize the current knowledge on the emerging role of Sfrp5 and Wnt5a in the pathogenesis of obesity and its comorbidities both in adults and children." (PMID 34371968, 2021). "It has been reported before that Wnt5a is expressed in higher level in visceral adipocytes and specially in obesity, and that this increased expression correlates with higher IL6 expression in human samples." (PMID 35111744, 2021). "Wnt5a and Sfrp5 appear to be critical players in the regulation of systemic inflammation in obesity and glucose homeostasis, as well as mediators between adipose tissue and other key metabolic organs, including the liver and the pancreas." (PMID 34371968, 2021). "This review summarizes the current evidence on the emerging role of Sfrp5 and Wnt5a in the pathogenesis of obesity, T2D and cardiovascular disease." (PMID 34371968, 2021). "The WNT5A protein, as a potent pro‐inflammatory signalling molecule, is strongly involved in a variety of inflammatory disorders such as obesity, type 2 diabetes mellitus (T2DM) and atherosclerosis." (PMID 32004418, 2020).
Obesity (continued). "Two reports describe increased expression of WNT5A mRNA and protein in lesional skin of patients with psoriasis, and interestingly, recent data suggest WNT5a to be a link between psoriasis, obesity and metabolic complications." (PMID 31089877, 2019). "Several studies suggested that wnt5a is also expressed in mammalian adipose tissue and expression in mice was induced by a high-fat diet and obesity." (PMID 31890678, 2019). "Study on myeloid Wnt5a knockout mice provided direct evidence that macrophage-derived Wnt5a mediated obesity-induced glucose metabolic dysfunction." (PMID 27608847, 2016). "In the same study two independent mouse models of obesity exhibited reduced sFRP5 expressions and an increased wnt5a/sFRP5 ratio in adipose tissue suggesting these two bioactive molecules to be involved in the development of obesity and type 2 diabetes." (PMID 22384249, 2012). "We next measured wnt5a and sFRP5 protein concentrations in serum samples of n = 12 lean control subjects and n = 23 subjects with obesity." (PMID 22384249, 2012). "In patients with obesity, however, wnt5a became significantly detectable consistent with low grade inflammation in such subjects." (PMID 22384249, 2012). "Our own group found wnt5a to be expressed in adipose tissue macrophages in human subjects with obesity and type 2 diabetes in vivo." (PMID 22384249, 2012). "Serum Wnt5a, leptin, and TNF-α levels increase in women with obesity and the A allele of TLR2 (Arg753Gln) SNP could be protective against obesity-associated metaflammation." (PMID 39837875, 2025). "When caused by obesity, SFRP5 attaches to and prevents Wnt5a." (PMID 36404859, 2022). "On the other hand, WNT5A pathway has been found to be remarkably more activated in VAT than in SAT in the presence of obesity, which is consistent with our results regarding WNT5A expression in VAT compared to that of the SAT in our whole cohort, the most part presenting MO." (PMID 36077270, 2022). "In addition, we found subcutaneous WATs more sensitively responded to obesity in terms of increases in adipocyte size and Wnt5a induction than epididymal WATs." (PMID 35478181, 2022). "This study shows Wnt5a might be a novel adipokine released by hypertrophic adipocytes to blood and suggests Wnt5a provides a molecular connection between obesity and obesity-related diseases in remote organs." (PMID 35478181, 2022). "We postulate that elevated levels of Wnt5a during obesity (released from the VAT) may promote the development and growth of the aggressive squamous subtype of PDAC through YAP-mediated mechanisms, although further studies are needed to confirm this model." (PMID 34680216, 2021). "In animal models of obesity and type 2 diabetes, Wnt5a triggers the activation of signaling pathways through JNK (c-jun N-terminal kinase) activation, and then contributes to low-grade inflammation, insulin resistance, and metabolic dysfunction in adipose tissue and atherosclerotic plaque." (PMID 33462195, 2021). "Therefore, Sfrp5 plays a pivotal role in the metabolic complications of obesity by inhibiting Wnt5a and the inflammation that the latter promotes." (PMID 34371968, 2021). "Sfrp5 is an adipokine which may play a protective role against obesity-related insulin resistance and T2D by binding to Wnt5a and improving insulin sensitivity." (PMID 34371968, 2021). "Their results also suggested that a failure to upregulate SFRP5 in obesity may lead to unrestrained pro-inflammatory actions of Wnt-5A, resulting in metabolic dysfunction." (PMID 30704061, 2019). "Based on these data, increases of canonical Wnt10b, β-catenin and non-canonical Wnt5a by RAL are strongly associated with the suppression of obesity during estrogen-deficiency." (PMID 31470850, 2019). "Stimulation of non-canonical Wnt signaling through the overexpression of WNT5A, which is important for inflammation in adipose tissue, is associated with obesity and NIDDM." (PMID 30678306, 2019).